ALKBH1 (alkB homolog 1, histone H2A dioxygenase)
Diseases named in the same sentence as ALKBH1 in open-access papers (continued):
Sharing a sentence is not in itself a finding about the gene and the disease.
Hypertension (3 papers, 2020 to 2022). The presence of chronic increased pressure in the systemic arterial system. "Thus, elevated ALKBH1 in VSMCs of hypertension models was directly associated with reduced 6mA DNA level in vivo and in vitro." (PMID 32283543, 2020). "Recent studies targeting hypertension has suggested 6mA levels as novel marker and its demethylase, ALKBH1 as probable therapeutic target to prevent hypertension through epigenetic programming." (PMID 35061109, 2022). "Our previous study determined that a reduction of 6mA by elevated ALKBH1 leads to the development of hypertension and atherosclerosis in vivo and in vitro." (PMID 35256595, 2022). "Their findings suggested 6mA as sensitive marker for diagnosis of hypertension and ALKBH1 as novel therapeutic target to prevent hypertension through epigenetic reprogramming because ALKBH1 mediates cross talk between 6mA DNA level and H1F1α activity." (PMID 35061109, 2022). "Collectively, our results demonstrate a potential epigenetic role for ALKBH1-6mA regulation in hypertension development, diagnosis and treatment." (PMID 32283543, 2020). "Elevated ALKBH1 (AlkB homolog 1), a demethylase of 6mA, level mediated this dynamic change in 6mA level in leukocytes and vascular smooth muscle cells in hypertension mouse and rat models." (PMID 32283543, 2020). "Elevated ALKBH1 level was responsible for decreased 6mA DNA level in leukocytes and VSMCs of in vivo and in vitro hypertension models." (PMID 32283543, 2020). "Our data suggest that ALKBH1 could provide a novel therapeutic target for preventing hypertension development by epigenetic reprogramming." (PMID 32283543, 2020). "Consistent with findings that ALKBH1 is a demethylase for 6mA promoting stem cell differentiation and tumorigenesis, our data suggest that elevated ALKBH1 level-reduced 6mA level in leukocytes and VSMCs is involved in hypertension development in human and mouse and rat models." (PMID 32283543, 2020). "However, future investigations are needed to determine whether ALKBH1-specific knockin and knockout mice could directly promote and prevent vascular remodeling during hypertension development." (PMID 32283543, 2020). "Similarly, ALKBH1, the demethyltransferase of 6mA, was upregulated and negatively associated with 6mA DNA level in VSMCs of hypertensive mice or rats; the level of aortic N6AMT1, the methyltransferase of 6mA by hypertension, showed no change." (PMID 32283543, 2020).
neuroblastoma (3 papers, 2024 to 2025). Neuroblastoma (NB) is the most common solid, extracranial childhood tumor. "Our research results showed that the ALKBH1 rs2267755C>T variant is significantly associated with reduced neuroblastoma risk." (PMID 38169562, 2024). "In the present study, we explored the role of the ALKBH1 SNPs in neuroblastoma risk for the first time." (PMID 38169562, 2024). "This study investigated the relationship between 6mA demethylase ALKBH1 and neuroblastoma susceptibility in Chinese children from the perspective of genetic polymorphism." (PMID 38169562, 2024). "In the present study, we genotyped the ALKBH1 single nucleotide polymorphisms (SNPs) in 402 neuroblastoma patients and 473 healthy controls by TaqMan assay." (PMID 38169562, 2024). "In general, we elucidated the relationship between ALKBH1 gene SNPs and neuroblastoma susceptibility." (PMID 38169562, 2024). "Among 4 newly identified ALKBH1 SNPs, the rs2267755 C>T is significantly associated with neuroblastoma risk in Chinese children." (PMID 38169562, 2024). "Given the crucial role of ALKBH1 in cancer, we conducted a comprehensive analysis to illuminate the relationship between the ALKBH1 gene SNPs and neuroblastoma susceptibility in Chinese children, providing new evidence for predicting the risk of neuroblastoma." (PMID 38169562, 2024). "Whether the ALKBH1 polymorphism contributes to neuroblastoma risk remains unclear." (PMID 38169562, 2024). "Therefore, we predicted ALKBH1 may be associated with neuroblastoma risk." (PMID 38169562, 2024). "However, it remains unclear whether ALKBH1 is associated with neuroblastoma risk." (PMID 38169562, 2024).
esophageal cancer (2 papers, 2021 to 2023). A primary or metastatic malignant neoplasm involving the esophagus. "Most regulators showed amplification in copy numbers, especially in colon cancer (COAD) and esophageal cancer (ESCA), while the CNV deletions were frequently found on TET2, ALKBH1, and DNMT1." (PMID 37332118, 2023).
lung adenocarcinoma (2 papers, 2021 to 2025). A carcinoma that arises from the lung and is characterized by the presence of malignant glandular epithelial cells. "A study analyzing various bioinformatics databases like ONCOMINE, TIMER, and Disease-Meth revealed significant upregulation of ALKBH1, ALKBH2, ALKBH4, ALKBH5, ALKBH7, and ALKBH8 in lung adenocarcinoma (LUAD) tissues compared to normal lung tissues." (PMID 40646842, 2025).
pancreatic adenocarcinoma (2 papers, 2021 to 2023). "In addition, individuals with pancreatic adenocarcinoma (PAAD), whose expression of the ‘‘eraser’’ gene ALKBH1 is low, have a worse prognosis in comparison to high expressers." (PMID 37679761, 2023).
breast tumors (1 paper, 2022). "To confirm the clinical findings, we queried a breast statistics database of 2136 samples and found decreased N6AMT1, but not ALKBH1 mRNA expression in nearly all types of breast tumors compared with normal breast." (PMID 35256595, 2022).
cocaine addiction (1 paper, 2020). "Twelve DEGs (Myct1, Gm21860, Ninj2, Fam183b, Lars2, Alkbh1, Fgf5, Frmd7, Tm6sf2, Wnt6, Batf3, and Clca1) were found to be regulated inversely among the overlap genes, which may be possible targets of RPA to disrupt the cocaine addiction process." (PMID 32489401, 2020).
dengue virus infection (1 paper, 2023). "Here we show that flaviviruses hijack the host tRNA epitranscriptome to promote expression of pro-viral proteins, with tRNA-modifying ALKBH1 acting as a host restriction factor in dengue virus infection." (PMID 37986976, 2023).
hyperphosphatemia (1 paper, 2022). Abnormally high level of phosphate in the blood. "Hyperphosphatemia was identified to convert the contractile phenotype of vascular smooth muscle cells to the osteogenic phenotype, during which DNA 6 mA demethylated by ALKBH1 facilitated OCT4 to recognize and bind to BMP2 promoter." (PMID 36581839, 2022).
low grade glioma (1 paper, 2022). A grade I or grade II glioma arising from the central nervous system. "However, high expression of ALKBH1 mRNA did not alter overall survival (OS) rates of both GBM and low-grade glioma (LGG)." (PMID 35501312, 2022).
lymph node metastasis (1 paper, 2023). "Upregulated ALKBH1 expression was significantly associated with lymph node metastasis (P = 0.0014), distant metastasis (P = 0.0091), and advanced AJCC stage (P = 0.0007)." (PMID 36550779, 2023).
nonalcoholic fatty liver disease (1 paper, 2024). "However, the demethylase ALKBH1 reduces the uptake and synthesis of lipids, leading to a decrease in hepatic lipid accumulation, thereby alleviating hepatic steatosis and the progression of nonalcoholic fatty liver disease (NAFLD)." (PMID 38902779, 2024).
osteoporosis (1 paper, 2022). A condition of reduced bone mass, with decreased cortical thickness and a decrease in the number and size of the trabeculae of cancellous bone (but normal chemical composition), resulting in increased fracture incidence. "In consideration of the pathologic role of Alkbh1 deficiency in triggering osteoporosis, we next investigated whether Alkbh1 overexpression could alleviate age‐related osteoporosis." (PMID 35018683, 2022). "Our findings demonstrated that Alkbh1 regulated BMSCs fate and bone‐fat balance during skeletal aging and provided a potential target for the treatment of osteoporosis." (PMID 35018683, 2022).
Wilms tumour (1 paper, 2025). "Second, Wilms tumour is a complex disease that is influenced by numerous genetic factors, and only three SNPs in the ALKBH1 gene cannot fully explain the risk of Wilms tumour development." (PMID 41017026, 2025). "We aimed to explore the association between SNPs in the ALKBH1 gene and susceptibility to Wilms tumour development." (PMID 41017026, 2025). "Our results revealed a significant association between the rs6494 polymorphism and susceptibility to Wilms tumour development, and the protective allele A of rs6494 was associated with decreased expression of ALKBH1 and increased expression of SNW1 and ADCK1." (PMID 41017026, 2025). "This is the first multicenter epidemiological study to investigate the associations between ALKBH1 genetic polymorphisms and risk of developing Wilms tumour in Chinese children." (PMID 41017026, 2025). "In conclusion, our study identified rs6494 T>A in the ALKBH1 gene as a susceptibility locus for WT, providing valuable insights into the etiological factors underlying Wilms tumour susceptibility." (PMID 41017026, 2025). "We then analysed the associations between the ALKBH1 gene polymorphisms and susceptibility to Wilms tumour development in subgroups separated by age, sex and clinical stage." (PMID 41017026, 2025). "The frequency of inferred haplotypes of ALKBH1 gene based on observed genotypes and their association with Wilms tumour risk." (PMID 41017026, 2025). "In this study, we investigated the potential roles of three SNPs (rs6494, rs1048147 and rs176942) in the ALKBH1 gene and their associations with susceptibility to Wilms tumour development." (PMID 41017026, 2025). "This accumulated evidence has led to the hypothesis that there is a potential association between ALKBH1 and the risk of Wilms tumour development." (PMID 41017026, 2025). "Finally, the underlying mechanism by which SNPs in ALKBH1 affect Wilms tumour risk awaits further investigation." (PMID 41017026, 2025). "However, no studies have explored the potential impact of polymorphisms in ALKBH1 on Wilms tumour risk thus far." (PMID 41017026, 2025). "Associations between ALKBH1 gene polymorphisms and Wilms tumour risk." (PMID 41017026, 2025). "Stratification analysis for association between ALKBH1 genotypes and Wilms tumour risk." (PMID 41017026, 2025). "It is reasonable to hypothesize that ALKBH1 most likely participates in the development of Wilms tumour by regulating the m1A modification of RNA, given the numerous SNPs that are associated with Wilms tumour risk and found in m1A modification genes." (PMID 41017026, 2025). "This raises an interesting question about which ALKBH1‐mediated methylation modifications contribute to the development of Wilms tumour." (PMID 41017026, 2025). "Overall, the impact of rs6494 on ALKBH1 potentially involves the regulation of nephrogenesis lineage differentiation, which contributes to the development of Wilms tumour." (PMID 41017026, 2025). "Taken together, these findings suggest that ALKBH1 may be involved in the development of Wilms tumour through diverse modification patterns." (PMID 41017026, 2025).
cancer (33 papers, 2012 to 2026). A tumor composed of atypical neoplastic, often pleomorphic cells that invade other tissues. "Next, the we performed Kaplan–Meier analysis to assess the association between ALKBH1 expression and overall survival (OS) in each of these cancer types." (PMID 38317214, 2024). "Using the mutation module in Pan-cancer, we analyzed the effect of ALKBH1 mutations on immune cell infiltration in various cancer types." (PMID 38317214, 2024). "We initially determined the frequency and type of ALKBH1 alterations in STAD, based on the STAD dataset from TCGA, and found that the ALKBH1 gene was mutated in 2.1% of all cancers by cBioPortal dataset." (PMID 38317214, 2024). "Our results showed that ALKBH1 mutations were the fourth most frequent in pan-cancer." (PMID 38317214, 2024). "When exploring the role of ALKBH1 across different cancers, we have found that expression levels of ALKBH1 have a significant correlation with patient prognosis." (PMID 40675967, 2025). "Looking ahead, it is worthwhile to explore the potential of ALKBH1 inhibitors and targeting matrix stiffness in cancer therapy." (PMID 40867005, 2025). "Despite similar biological phenotypes, the pattern of ALKBH1 modification and its molecular process varies among these cancers." (PMID 41017026, 2025). "For instance, deregulations of tRNA modification enzyme genes METTL1 and ALKBH1 induced impaired translation and aberrant cancer progression in vitro and in vivo." (PMID 39695074, 2024). "ALKBH1's interaction with diverse substrates highlighted the significance of genomic DNA's N6mA modification, especially in cancer." (PMID 38317214, 2024). "To gain a more comprehensive understanding of ALKBH1 expression in various contexts, we examined its expression levels in different sample types, cancer stages, metastatic stages, and Helicobacter pylori infection in The Cancer Genome Atlas (TCGA) dataset." (PMID 38317214, 2024). "To delve further into the impact of ALKBH1 mutations on STAD, we explored their interactions with other common genes involved in cancer progression, including TTN, PBRM1, and SETD2." (PMID 38317214, 2024). "To further investigate the potential clinical significance of ALKBH1, we examined its expression levels in various types of cancer and evaluated its prognostic value." (PMID 38317214, 2024). "By the more advanced approaches like bioinformatics, and single-cell sequencing, we can find the N6mA gene loci bound by ALKBH1 in different cancers and the pathways regulated." (PMID 37007161, 2023). "The 6mA levels were higher in glioblastoma cells compared with normal tissues, and the 6mA demethylase ALKBH1 has also been considered as a potential new target for cancer treatment." (PMID 37762200, 2023). "Accumulating studies indicate that ALKBH1 is related to a range of cancers, although its role in different cancers is inconsistent." (PMID 36550779, 2023). "Among the multiple substrates of ALKBH1, N6mA of genomic DNA has the most critical effect on cancer." (PMID 37007161, 2023). "All findings indicate that silencing ALKBH1 gene expression increases the growth and invasiveness of cancer cells." (PMID 33779693, 2021). "As our comprehension of the mechanisms through which ALKBH1 operates in diverse cancers deepens, new therapeutic strategies may be developed in the future to target the expression and function of ALKBH1, thereby improving patient treatment outcomes." (PMID 40675967, 2025). "The role of the demethylase ALKBH1, which is known for its association with diverse cancers, in WT has never been explored." (PMID 41017026, 2025). "However, accumulating studies indicate that ALKBH1 contributes to the development of a range of cancers through diverse modification patterns, and its role across different cancer types is inconsistent." (PMID 41017026, 2025). "We will comprehensively explore the roles played by ALKBH1 gene variations in various cancers." (PMID 38317214, 2024).
cancer (continued). "Thereinto, silencing of ALKBH1 significantly impaired the growth of cancer xenografts in vivo." (PMID 38169562, 2024). "To test whether the expression of ALKBH1 was compromised in cancer cells, we measured the RNA levels of NSUN3 and ALKBH1." (PMID 35768510, 2022). "Since ALKBH1 is a demethylase of m1A in mRNA, it is interesting to consider whether its function in cancers is related to its demethylation activity towards m1A in mRNA." (PMID 33779693, 2021). "Moreover, ALKBH1 is markedly overexpressed in advanced tumors that are high metastatic, and exhibit high malignancy, underscoring its potential role as a biomarker for aggressive cancer behavior." (PMID 40675967, 2025). "However, the function of ALKBH1 in cancer seems to vary depending on the tissue type." (PMID 38317214, 2024). "ALKBH1 and NSUN are RNA modifiers that regulate cell fate, and E2F is upregulated in several cancers as it plays an important role in the cell cycle." (PMID 40135438, 2025). "Lastly, while we have explored the stiffness-ALKBH1-6 mA mechanism in CRC, a genome-wide analysis would be valuable to determine its universality across various cancers, potentially paving the way for pan-cancer treatments." (PMID 40867005, 2025). "Like ALKBH1, ALKBH3, as enzymes that can bind to tRNA and affect cancer prognosis by regulating protein synthesis, is also a new research direction." (PMID 37007161, 2023). "In human cancer tissues, 6mA showed a downward trend, accompanied by the downregulation of N6AMT1 and the upregulation of ALKBH1." (PMID 37762200, 2023). "ALKBH3 (p < 0.001), TRMT61A (p < 0.001), YTHDF1 (p < 0.001), ALKBH1 (p < 0.001), and TRMT6 (p < 0.001) in cancer tissues were significantly up-regulated compared to those in normal tissues (p < 0.001)." (PMID 34195072, 2021). "Using western blot (WB) analysis, we detected overexpression of seven out of the nine ALKBH proteins (ALKBH1, 2, 3, 4, 5, 8, and FTO) in HNSCC cancer tissues, as compared to the surrounding, unaffected tissue." (PMID 31519943, 2019). "Further, silencing of ALKBH1, 4, 5, and FTO markedly decreased HeLa cancer cell survival, suggesting involvement of these ALKBHs in cancer development by DNA/RNA/protein modification." (PMID 31519943, 2019). "To evaluate its function in ATC drug resistance, we examined correlations between the expression of 12 m5C regulators [NSUN2-7, TRDMT1 (writers); ALKBH1, TET2, ALKBH3 (erasers); YBX1 and ALYREF (readers)] and drug sensitivity in the Cancer Therapeutics Response Portal (CTRP)." (PMID 40083919, 2025). "Finally, we accessed the Cancer Drug Sensitivity Genomics (GDSC) and Cancer Cell Lineage Encyclopedia (CCLE) cell repositories, and identified ALKBH1 as a validated drug candidate in the context of targeting." (PMID 38317214, 2024). "The positive pan-cancer correlations with m1A RNA methylation regulatory proteins YTHDF2 and ALKBH1, m5C methylation regulatory proteins DNMT1, DNMT3B, and ALYREF, and m6C RNA methylation regulatory proteins HNRNPC, HNRNPA2B1, and ELAVL1 were particularly significant." (PMID 36090896, 2022). "Additionally, our previous work has identified the DNA demethylase ALKBH1 as critical to GSC survival, thus suggesting ALKBH1 as a promising target for cancer therapy." (PMID 32296573, 2020). "In the cancer tissue, we observed a similar correlation involving ALKBH5-FTO, ALKBH3-ALKBH5, and ALKBH1-ALKBH5, but also noted that the level of ALKBH2 was correlated with that of ALKBH5 and ALKBH1 with ALKBH3." (PMID 31519943, 2019). "Thus, efforts were worthy of being paid to study whether or not ALKBH family members such as ALKBH1 could serve as therapeutic target(s) for clinical cancer therapy." (PMID 30405719, 2018). "So far, the roles of ALKBH1, ALKBH2, and ALKBH3 in cancer regulation have not been studied much." (PMID 37007161, 2023).